MEG3 (maternally expressed 3)
Diseases named in the same sentence as MEG3 in open-access papers (continued):
Sharing a sentence is not in itself a finding about the gene and the disease.
tumor (598 papers, 2005 to 2026). "Maternally expressed gene 3 (MEG3) is an imprinted gene, which encodes about 1.6 kb long non-coding RNA and has been indicated as a tumor suppressor." (PMID 39049088, 2024). "Among overall CRC patients, MEG3 rs941576 was associated with lymph node (LN) metastasis and tumor stage, serum MEG3 was negatively correlated with tumor stage, while SIRT1 was correlated with the anatomical site." (PMID 38704452, 2024). "Linear regression analysis demonstrated that the levels of AGAP2-AS1 and MEG3 were negatively associated in tumor samples." (PMID 39124865, 2024). "For instance, MEG3 coated with nanoparticles has been shown to cause a significant reduction in the expression of tumor markers and decreased expression of hepatic PCNA." (PMID 39448589, 2024). "To evaluate the role of MEG3 in mediating the effects of the GNAS mutation on tumor invasion, we examined the effects of MEG3 knockdown in GH3 cells expressing mutant GNAS." (PMID 38827318, 2024). "Although MEG3 is a widely known tumour suppressor gene and its loss is associated with several cancer types, here we reported that MEG3 inhibition can be used for improving the efficiency of known chemotherapeutic drug sensitivity." (PMID 37525401, 2023). "In most primary tumors, the hypermethylation of the maternal allele of MEG3 is down-regulated, and its ectopic expression will reduce tumor progression; Therefore, MEG3 usually acts as a tumor suppressor." (PMID 37251826, 2023). "Inhibition of miR-21-5p restrained cell colony formation and invasion and abolished MEG3-knockdown caused tumor-promoting effects in NSCLC cells." (PMID 37308993, 2023). "Lastly, a group of cells, emerged as specifically expressing non‐coding RNAs with a tumor‐associated role, such as MEG3, NEAT1, and FTX (Fig EV5C and D)." (PMID 38037472, 2023). "Mac Mrc1-enriched spots were enriched at the tumour periphery, and correlation analysis revealed a significant positive association between Mac Mrc1 and Meg3, Fbln1 and Lrrc15 CAF subtypes, which suggested proximity." (PMID 37605008, 2023). "MEG3 has a tumour suppressor role in normal tissues and its loss of function has been associated with various cancer types including bladder, breast, bone marrow, cervix, colon, liver lung and meninges." (PMID 37525401, 2023). "Studies have demonstrated that promoter hypermethylation and gene deletion resulted in the loss of MEG3 in tumor tissues and cancer cell lines." (PMID 36851033, 2023). "Here, we further explored the anti‐tumour effects of MEG3 in vivo and attempted to clarify the specific molecular mechanisms underlying the regulatory loop of MEG3 and EZH2." (PMID 35257481, 2022). "Herein, we summarize recent knowledge regarding the role of MEG3 in regulating tumor hallmarks as well as the underlying molecular mechanisms." (PMID 36551518, 2022). "From the single-cell data we examined, there was clear heterogeneity in the expression of MEG3 among tumor-associated fibroblasts." (PMID 36231143, 2022). "Low expression or deletion of MEG3 is associated with large tumor size, advanced FIGO stage, deep infiltration, early metastasis, and poor survival." (PMID 36544907, 2022). "Given our finding that the proportion of CAFs was highly associated with MEG3 expression in our bulk tumor samples, we aimed to determine if the MEG3 was being expressed by tumor cells that were recruiting CAFs, or if CAFs were directly expressing MEG3." (PMID 36231143, 2022). "LncRNA encoded by MEG3 was found to have tumor-suppressive abilities in different types of tumors, including glioma, gastric cancer, and melanoma." (PMID 36142783, 2022).
tumor (continued). "Meg3 encodes an lncRNA which functions as a tumor suppressor and serves as a surrogate marker of downstream proliferation-inhibiting miRNAs." (PMID 35676718, 2022). "Another study generated similar results MEG3 was associated with tumor progression and poor prognosis." (PMID 36544907, 2022). "Aberrant MEG3 expression has been observed in various tumors and is closely linked with tumor cell proliferation." (PMID 36551518, 2022). "Numerous studies have implicated the involvement of MEG3 in a myriad of biological processes, notably as a tumor suppressor." (PMID 35047570, 2021). "Down-regulation of lncRNA ncRuPAR and MEG3 in GC samples was associated with lymph node metastases, distant metastases, tumor size, and tumor invasion depth." (PMID 33295609, 2021). "Both have good diagnostic efficacy, suggesting that LncRNA MEG3 and miR-543 can be applied as tumor markers." (PMID 34399782, 2021). "On the other hand, recent studies have implicated MEG3 in the regulation of different oncogenic and tumor-suppressive gene networks, possibly through an activity as a molecular decoy for cancer-associated microRNAs." (PMID 32295169, 2020). "Multiple molecular mechanisms, including gene deletion and promoter hypermethylation, contribute to the loss of MEG3 expression in tumor cells." (PMID 33363153, 2020). "Overall, results from this study demonstrated that decreased MEG3 is a hallmark for malignancy and tumor progression in HGSOC." (PMID 32295169, 2020). "Long non-coding RNA (lncRNA) MEG3, an identified tumor suppressor, has been implicated in the development of various cancers." (PMID 31488093, 2019). "The expression of MEG3 is negatively associated with the histological grade, tumor invasion, and tumor node metastasis stage of CRC patients, and overexpression of MEG3 inhibits the proliferation of CRC cells in vitro and in vivo." (PMID 31693738, 2019). "MEG3 rs10132552 was significantly associated with tumor size in its recessive model (p = 0.022) and additive model (p = 0.007)." (PMID 31488093, 2019). "Among most tumor-associated lncRNAs, the lncRNA MEG3 (maternally expressed gene 3) has attracted much attention." (PMID 31584879, 2019). "A previous study showed that down-regulation of MEG3 was associated with the expression of tumor genes in epithelial cells." (PMID 31888661, 2019). "Maternally Expressed Gene 3 (MEG3) encodes a tumor suppressor lncRNA that is expressed in many normal tissues." (PMID 29495592, 2018). "Both of these main features are associated with tumor suppression and a putative correlation has been also proposed between MEG3 upregulation and physiological aging and replicative senescence of stem and progenitor cells." (PMID 30395586, 2018). "Maternally Expressed Gene 3 (MEG3) is an imprinted gene located at chromosome 14q32 and encodes a lncRNA which is pervasively expressed in normal tissues and confirmed as a tumor suppressor." (PMID 29416703, 2018). "Maternal expressed gene 3 (MEG3) is a maternal imprinted gene encoding a lncRNA that acts as a tumor suppressor in various tumors." (PMID 30581678, 2018). "It has been confirmed that MEG3 encodes an lncRNA which is suggested to function as a tumor suppressor and has been shown to involve in a variety of cancers." (PMID 29449541, 2018). "Maternally expressed gene 3 (MEG3) encodes an lncRNA which is suggested to function as a tumor suppressor and has been showed to involve in a variety of cancers." (PMID 29449541, 2018). "Overexpression of Gtl2/Meg3 in various tumor cell lines caused a reduction in proliferation, lending support to its purported tumor suppressor function." (PMID 29996488, 2018).
tumor (continued). "MEG3 has been extensively associated with multiple human cancer types and is proposed as a tumor suppressor and a negative regulator of angiogenesis." (PMID 30395586, 2018). "Maternally expressed gene 3 (MEG3), which located in chromosome 14q32 and encodes a lncRNA, represents as an important tumor suppressor gene in human." (PMID 29287592, 2017). "Maternally expressed gene 3 (Meg3) encodes a lncRNA produced by various normal tissues, which plays the role of tumor suppressor." (PMID 29206174, 2017). "In the cell line and TARGET datasets, we also studied the methylation patterns of the MEG3 imprinting control region on 14q32 and their association with miRNA expression and tumor aggressiveness." (PMID 28506242, 2017). "The loss of MEG3 expression, its deletion from genomic DNA and the degree of promoter methylation are associated with aggressive tumor growth." (PMID 26637808, 2016). "Concerning MEG3, its downregulation was associated not only with markers of poor prognosis, namely, large tumor size, advanced pathological stage and increased depth of invasion, but also with shorter OS." (PMID 26064090, 2015). "Our findings indicated that MEG3 was down-regulated in GC tissues, and a lower level of MEG3 was associated with tumor stage and metastasis." (PMID 26253106, 2015). "Maternally Expressed Gene 3 (MEG3) encodes a lncRNA which is suggested to function as a tumor suppressor." (PMID 26444285, 2015). "For example, MEG3 (maternally expressed gene 3), is an imprinted, maternally expressed gene, encoding a lncRNA that functions as a tumor suppressor." (PMID 26230935, 2015). "Loss of MEG3 expression has been found in many tumours, and re-expression of MEG3 can inhibit tumour proliferation in vitro." (PMID 25297942, 2014). "Re-expression of MEG3 inhibits tumor cell proliferation in culture and colony formation in soft agar and the underlying mechanism of growth inhibition is partly the result of MEG3-induced apoptosis." (PMID 24006935, 2013). "A study conducted by Tang and colleagues demonstrated the tumor-suppressive role of MEG3 lncRNA, showing that mutations in the α subunit of the stimulatory G protein (GNAS) upregulate MEG3 lncRNA expression and are associated with less invasive growth hormone-secreting PitNETs." (PMID 41141357, 2025). "Human maternally expressed gene 3 (MEG3) encodes an RNA transcript that exhibits tumor suppressive ncRNA functions (lncRNA MEG3) with an unknown contribution to cellular processes in its limited translated form." (PMID 38279330, 2024). "Furthermore, patients carrying MEG3 rs7158663 AA genotype had an increased risk of T3 + T4 local tumor invasion (OR: 2.771, p = 0.011) and N2 + N3 lymph node status (OR: 2.511, p = 0.023) than those with GG genotype." (PMID 39049088, 2024). "A defect in the expression of MEG3 can lead to various diseases including cancer as a result of the disruption caused in the regulation of cellular proliferation and its putative role as a tumour suppressor." (PMID 37525401, 2023). "MEG3 was the first tumour suppressor lncRNA identified, has been demonstrated to have a pathogenic role in a number of cancer models, and is down-regulated in a number of primary tumours in comparison to matched normal tissues." (PMID 37169950, 2023).
tumor (continued). "MEG3 is an imprinted gene located in the DLK1-MEG3 locus present on chromosome 14q32.3 in humans, which encodes an alternatively spliced long noncoding RNA of ~ 1.7 kb that functions as tumor suppressor; its expression is lost in various human cancer cell lines." (PMID 35796900, 2022). "The mechanisms underlying the tumor suppressive effects of MEG3 could be mediated through epigenetic regulation of c-Met." (PMID 34439315, 2021). "In BRCA, MEG3’s downregulation is associated with poor overall survival and tumor staging." (PMID 34136413, 2021). "Furthermore, the tumor-suppressive lncRNA MEG3 is associated with increased proliferation and decreased apoptosis of GBC cells." (PMID 34944491, 2021). "However, the mechanism underlying the putative tumor suppressive role of MEG3 in GH-secreting pituitary adenomas needs further investigation." (PMID 34484116, 2021). "The decreased expression of MEG3 is also considered a hallmark for tumor progression in OC." (PMID 34885213, 2021). "The loss of MEG3 expression has also been associated with tumor grade in meningiomas." (PMID 33142861, 2020). "This suggests that MEG3 might serve as a tumor-suppressive lncRNA in BTC via its ability to cause degradation of EZH2." (PMID 32331331, 2020). "It is worthy to note, however, that according to the Cancer LncRNA Census (CLC), a compilation of 122 GENCODE lncRNAs with causal roles in cancer phenotypes, MEG3 is among the top-ranked lncRNAs, on the basis of available data relative to its role as tumor suppressor." (PMID 32295169, 2020). "Studies on the relationship between MEG3 SNP and tumor susceptibility have also been reported." (PMID 33119060, 2020). "Our study, for the first time reveals that the MEG3 expression is downregulated in CC and higher tumor grade is related to higher MEG3 expression, indicating that MEG3 might act as a diagnostic marker for the pathological staging." (PMID 31729423, 2019). "Our study combined with TCGA database has revealed that MEG3 is associated with tumor staging." (PMID 31729423, 2019). "MEG3 is located on human chromosome 14q32.3 and encodes a tumor suppressor lncRNA." (PMID 29721215, 2018). "Taken together, MEG3 is a tumor suppressor and might be considered a prospective diagnostic, predictive and therapeutic biomarker in HCC." (PMID 30105249, 2018). "Maternally expressed gene 3 (MEG3, mouse homolog Gtl2) encodes a long noncoding RNA (lncRNA) that is expressed in many normal tissues, but is suppressed in various cancer cell lines and tumors, suggesting it plays a functional role as a tumor suppressor." (PMID 27832204, 2016). "As a tumor suppressor gene, MEG3 is associated with tumorigenesis." (PMID 26136615, 2015). "The loss of MEG3 expression contributes to the progression of various tumours, including NSCLC." (PMID 25297942, 2014).
tumor (continued). "MEG3 encodes a noncoding RNA that acts as an imprinted tumor suppressor gene." (PMID 22666422, 2012). "Thus, it is speculated that the reductions in MEG3 transcripts by Cd cause the loss of MEG3 tumor suppression function, resulting in increased susceptibility to cancer." (PMID 36851033, 2023). "Notably, Meg3 deficiency dramatically attenuated tumor growth in ApcminmiR-708−/− mice, hinting that the combined application of agomirs of Meg3 and antagomirs of miR-708 might contribute to therapy of CRC in the clinic." (PMID 34934045, 2021). "The long non-coding RNA Meg3, which functions as a tumor suppressor, has been reported to be abnormal in multiple tumorigenesis events; however, the underlying mechanism by which Meg3 contributes to the malignant proliferation of colonic stem cells remains unclear." (PMID 34934045, 2021). "For instance, overexpression of the HOTAIR lncRNA correlates with cancers that are more aggressive, whereas MEG3 lncRNA may act as a tumor suppressor and its downregulation has been associated with the development of a variety of human cancer involving the liver, breast, uterus, and ovary." (PMID 34204445, 2021). "Indeed, MEG3 down-regulation or silencing has been associated with increased angiogenesis in human tumours, Gtl2 knockout mouse models and a rat model of tissue repair after ischaemic brain injury.This is regulated via activation of angiogenesis related genes including Vegf, βFGF and TGF-β1." (PMID 32822966, 2020). "Indeed, the chromosome alterations affecting the H19, KCNQ1OT1, PLAGL1 and GNAS DMRs also affected one or more WT driver genes in all analyzed cases, and the chromosome variants affecting the MEST, GRB10 and MEG3 DMRs also affected tumor driver genes in at least 83% of cases." (PMID 33217932, 2020). "Therefore, MEG3 may act as a novel tumor suppressor, and the association between MEG3 and cancer has received increasing attention." (PMID 26992211, 2016). "The long non-coding RNA MEG3 (Maternally Expressed Gene 3), located on chromosome 14q32.3, has been identified as a tumor suppressor in various cancers." (PMID 41480643, 2026). "The interaction indicated that MEG3 acts as a tumour suppressor, whereas miR-184 functions as a tumour promoter in this context." (PMID 41379397, 2025). "As a tumor-suppressor lncRNA, MEG3 acts as a ceRNA against miR-205-5p, inhibiting cell proliferation by downregulating the expression of PTEN and SMAD4 in the SKOV3 and OVCAR8 OC cell lines." (PMID 39941838, 2025). "Among them, expression of MEG3 is frequently lost/decreased in different malignancies and accumulated evidence supports that MEG3 functions as a tumor suppressor." (PMID 40548301, 2025). "Low MEG-3 expression correlated with advanced tumor stages, poor treatment response, and adverse prognostic factors, while high expression was associated with better survival outcomes (p < 0.001)." (PMID 40242248, 2025). "The tumor-suppressor lncRNA MEG3 positively regulates PTEN and reduces cell migration in SKOV3 OC cells through the induction of cell apoptosis." (PMID 39941838, 2025). "MEG3 has tumor-suppressive properties since it regulates the proliferation of the cells and induces apoptosis and low levels of MEG3 mRNA correlate with increased tumor growth rate and poor survival." (PMID 40625740, 2025). "On the other hand, some lncRNAs, such as MEG3, act as tumor suppressors by inhibiting EMT and limiting tumor progression." (PMID 40362280, 2025).